MIR380 (microRNA 380)
Synonyms: hsa-mir-380; MIR380-3p; MIRN380; mir-380
Gene: MicroRNA gene on chromosome 14 (101,025,017 to 101,025,077, forward strand). Ensembl gene ENSG00000198982.
Homologues: Orthologues: chimpanzee ptr-mir-380 (100% identical).